TLR2 (toll like receptor 2)
Diseases named in the same sentence as TLR2 in open-access papers (continued):
Sharing a sentence is not in itself a finding about the gene and the disease.
psoriasis (35 papers, 2013 to 2025). An autoimmune condition characterized by red, well-delineated plaques with silvery scales that are usually on the extensor surfaces and scalp. "Another study revealed that the TLR2-rs4696480 AA genotype is related to a higher risk of developing psoriasis in the Turkish population." (PMID 34790055, 2021). "We show here that TLR2 deficiency unexpectedly exacerbates psoriasis-like skin inflammation through a decrease in regulatory T cells (Tregs) and impaired IL-10 production by Tregs and DCs." (PMID 33202847, 2020). "In addition to S100A7 and p-STAT3, the expression profiles of further psoriasis associated secreted immune mediators of the wild type and TLR2 or TLR3 KO epidermis models after stimulation with Pam2CSK4 or poly(I:C) were investigated with a multiplex assay." (PMID 40995100, 2025). "However, the patients with late onset psoriasis were more likely to carry allele G in the Arg753Gln TLR2 polymorphism, whereas allele T in the -1237 T/C TLR9 polymorphism was statistically more frequent in the patients with early onset psoriasis." (PMID 34790055, 2021). "However, in the Turkish population, the TLR2 SNP (rs4696480) is strongly associated with the heritability of psoriasis (Sabah-Özcan and Gürel, 2019)." (PMID 33510592, 2021). "Thus, it may be hypothesized that Hsp70 not only interacted with Treg-associated TLR2, but also directly interfered as damage-associated molecular pattern with psoriasis-specific signaling of TLR7/8." (PMID 33708208, 2021). "Summing up, we showed in in vitro epidermis models that the specific activation of TLR2 or TLR3 in keratinocytes induced the expression of psoriasis markers, especially of chemokines that are related to neutrophil recruitment." (PMID 40995100, 2025). "In a murine psoriasis model, TLR2 signaling contributed significantly to the itching by mediating the expression of CXCL1/2, IL-31, IL-33, ST2, IL-6, and TNF-α." (PMID 40995100, 2025). "In psoriasis, the persistent activation of TLRs, particularly TLR2 and TLR4, along with sustained NF-κB signaling, drives chronic inflammation and promotes the differentiation and expansion of pathogenic Th1 and Th17 cells." (PMID 40558675, 2025). "Among them, HSP60, HSP70, and HSP90 are mainly involved in psoriasis and act through receptors such as TLR2, TLR4, and CD91." (PMID 38255845, 2024). "A study conducted on 175 patients with psoriasis and 170 healthy controls found that genotype and allele frequencies for Arg753Gln TLR2 and -1237 T/C TLR9 gene polymorphisms in patients with psoriasis were similar to those in healthy controls." (PMID 34790055, 2021). "In conclusion, our results demonstrate that TLR2 has an important role in the pathophysiology of psoriasis." (PMID 33202847, 2020). "In this study, we investigated the possible roles of TLR2 in the development of psoriasis, using a mouse psoriasis model induced by imiquimod, a ligand for TLR7." (PMID 33202847, 2020). "In this study, we have shown that ozone treatment can significantly inhibit the TLR2/NF-κB signaling pathway in psoriatic lesions, thereby attenuating the local inflammatory response of psoriasis." (PMID 32398953, 2020). "Taken together, our results suggest that TLR2 signaling directly enhances Treg proliferation and IL-10 production by Tregs and DCs, suppressing imiquimod-induced psoriasis-like skin inflammation." (PMID 33202847, 2020). "We found that topical ozone treatment significantly decreased the IMQ-induced expression levels of TLR2, P50, and P65 in the mouse model and in patients with psoriasis." (PMID 32398953, 2020). "In this study, we investigated the role of TLR2 in psoriasis using imiquimod-induced psoriasis-like dermatitis." (PMID 33202847, 2020). "We next examined the mRNA levels of psoriasis-related cytokines in the imiquimod-induced psoriasiform skin lesions in WT and TLR2 KO mice." (PMID 33202847, 2020).
psoriasis (continued). "High-throughput sequencing confirmed that IMQ-induced activation of toll-like receptor 2 (TLR2)/ nuclear factor-κB (NF-κB) signaling pathway was significantly suppressed in psoriasis-like lesions after topical ozone treatment." (PMID 32398953, 2020). "Many studies have shown that the TLR2/NF-κB signaling pathway promotes the release of multiple inflammatory factors in psoriasis lesions, aggravating the inflammatory response of psoriasis lesions." (PMID 32398953, 2020). "HSP60, HSP70, and Gp96 function as host derived ligands for toll-like receptors (TLR2) and play a role in the pathogenesis of RA and psoriasis." (PMID 23844278, 2013). "Emerging evidence suggests that SARS-CoV-2 may trigger new-onset or exacerbate existing psoriasis, likely through viral protein-induced activation of toll-like receptors (TLR2 and TLR4)." (PMID 40558675, 2025). "SNPs in TLR2, TNF, SLC12A8, ZNF816A and TNFAIP3 genes were associated with 3-month response (measured as PASI90 and absolute PASI < 1) to Secukinumab and Ixekinumab in 19 psoriasis patients." (PMID 41153404, 2025). "For instance, one study showed that rs4696480 of TLR2 may have significant effects on the heritability of psoriasis in the Turkish population." (PMID 36386838, 2022). "Furthermore, TLR2 variants (e.g., rs4696480 and rs11938228) have been shown to be associated with the response to anti-TNF treatment in patients with psoriasis." (PMID 35517818, 2022). "Furthermore, cytoplasmic TLR2 was mainly detected on basal keratinocytes in normal skin but was found to be highly expressed by the upper layer of epidermis in psoriasis lesions." (PMID 34790055, 2021). "In general, TLR1 and TLR2 were expressed in the upper and middle epidermis of psoriasis lesions." (PMID 34790055, 2021). "The role of TLR2 in psoriasis, however, remains to be elucidated." (PMID 33202847, 2020). "This study demonstrated whether and how TLR2 was involved in the pathogenesis of psoriasis using an imiquimod-induced psoriasiform dermatitis." (PMID 33202847, 2020). "TLR2 signaling promotes IL-10 production from DCs and Tregs and proliferation of Tregs, resulting in a decreased production of inflammatory cytokines and a marked attenuation of imiquimod-induced psoriasis skin inflammation." (PMID 33202847, 2020). "Our results demonstrate that TLR2 plays a pivotal role in the pathophysiology of psoriasis, suggesting that enhancement of TLR2 signaling may be a novel therapeutic approach to psoriasis." (PMID 33202847, 2020). "Cell-specific delivery of TLR2 signaling may be a novel therapeutic approach to psoriasis." (PMID 33202847, 2020). "Moreover, our findings have suggested TLR2 blocking agents, which may be developed soon, can exacerbate psoriasis by decreasing Tregs and IL-10 production." (PMID 33202847, 2020). "Enhancement of TLR2 signaling may be a new therapeutic strategy for psoriasis." (PMID 33202847, 2020). "The roles of TLR2 or TLR4 in psoriasis still remain unclear." (PMID 31815151, 2019). "TLR2 and TLR4 expressions are heightened in peripheral blood mononuclear cells and keratinocytes of psoriasis patients." (PMID 39859462, 2025). "In this work, we strived to shed more light on the role of TLR2 and TLR3 in keratinocytes for psoriasis and evaluate both receptors as a potential target for psoriasis therapies." (PMID 40995100, 2025). "In this work, we demonstrated a strong correlation between TLR2 and TLR3 activation in keratinocytes and expression of psoriasis markers." (PMID 40995100, 2025). "To analyze the role of TLR2 and TLR3 in psoriasis, we used 3D in vitro epidermis models for all experiments which mimic the complex stratification of the human skin." (PMID 40995100, 2025). "We demonstrated that treatment of in vitro epidermis models with the TLR2 agonist Pam2CSK4 and the TLR3 agonist poly(I:C) induced the expression of the psoriasis marker S100A7." (PMID 40995100, 2025).
psoriasis (continued). "By focusing on the activation profile of platelets and their interaction with immune cells, we identify cell-surface proteins CD32+CD154+ and TLR2+TLR4+, distinguishing unique platelet subsets in psoriasis patients." (PMID 41350257, 2025). "Finally, we conducted a replication analysis for SNPs in the TLR2, TLR5, and ANKRD55 genes, which were previously associated with treatment response to IL-23 inhibitors in a pre-selected SNP association study of a cohort of 18 patients with moderate-to-severe psoriasis from Spain." (PMID 41153410, 2025). "The expression of Toll-like receptor 2(TLR2) and TLR4 in the outer keratinocytes and peripheral blood mononuclear cells of patients with psoriasis is increased." (PMID 34215260, 2021). "Our data showed that psoriasis-like skin diseases activated TLR receptors based on skin lesions, which increased the expression of TLR2 and TLR4, and then activated MyD88 receptors and promoted the expression of MyD88 protein." (PMID 32090080, 2020). "They showed that the percentages of TLR-2+ and TLR-4+ lymphocytes are higher in patients with psoriasis than in the general population." (PMID 31554206, 2019). "The expression of TLR2 and TLR4 on peripheral blood mononuclear cells and keratinocytes is elevated in patients with psoriasis." (PMID 31815151, 2019). "In TLR2 and TLR3 KO epidermis models the treatment with TLR2 or TLR3 agonists did not induce the expression of psoriasis markers." (PMID 40995100, 2025). "In conclusion, elevated expression levels of TLR1, TLR2, TLR4, TLR7, and TLR9 may facilitate the occurrence of psoriasis." (PMID 34790055, 2021). "In order to examine whether topical ozone could inhibit TLR2/NF-κB signaling, we used immunohistochemistry to characterize the expression profiles of TLR2, P50, and P65 in IMQ-induced psoriasis-like lesions and in patients." (PMID 32398953, 2020). "Thus, TLR2 and TLR3 activation in keratinocytes individually contributes significantly to inducing the release of cytokines and other immune modulators characteristic for a psoriasis like inflammation in 3D epidermis models." (PMID 40995100, 2025). "Furthermore, HMGB1 upregulates the expression of TLR2, TLR4, and RAGE in the skin lesion area of psoriasis and activates the inflammasome and NF-κB pathway in keratinocytes to promote IL-18 secretion, which would aggravate the condition of IMQ model psoriasis mice." (PMID 38255845, 2024). "A study conducted on eight samples of normal skin and 15 samples of lesional and non-lesional biopsies from patients with psoriasis demonstrated that TLR1, TLR2, and TLR5 are constitutively expressed in the keratinocytes of normal skin." (PMID 34790055, 2021).
atopic dermatitis (34 papers, 2012 to 2025). "Toll-like receptor 2 genes (TLR2)-16934A > T polymorphism can affect its transcriptional activity and is associated with Scoring Atopic Dermatitis (SCORAD), which makes it to be a predictor of AD severity." (PMID 36465933, 2022). "The release of TLR2 agonists by skin-associated bacteria is thought to contribute to local inflammation, in particular in chronic disorders such as atopic dermatitis." (PMID 30459192, 2018). "Genotyping for TLR2 (R753Q and A-16934T) single nucleotide polymorphisms was performed in both atopic dermatitis patients and controls." (PMID 28443596, 2017). "The thymine allele frequency for the TLR2 A-16934T single nucleotide polymorphism in the atopic dermatitis group was 46.43%, and the adenine allele frequency was 53.57%, respectively." (PMID 28443596, 2017). "In general, the TLR2 gene G allele frequencies were 90,0% in the group of patients with atopic dermatitis and 97,0% in the control group." (PMID 28593178, 2017). "Impaired Toll-like receptor 2 (TLR2) function has been associated with the pathogenesis of atopic dermatitis (AD)." (PMID 26682905, 2015). "Moreover, atopic dermatitis patients with a TLR2 Arg753Gln gene polymorphism showed an increase in IL-6 and IL-12 levels as compared to patients with no mutation in the TLR2 gene upon TLR2 agonist stimulation of the monocytes." (PMID 40006996, 2025). "A recent study identified a specific polymorphism of TLR2-5 and -9 in patients with atopic eczema." (PMID 35011650, 2021). "Levels of IL-12 and IL-6 cytokines were significantly increased, which could explain the increased inflammation in the skin of patients with atopic dermatitis who presented this TLR2 mutation." (PMID 31781672, 2019). "Impaired TLR2 function has been associated with the pathogenesis of atopic dermatitis (AD)." (PMID 31815151, 2019). "In atopic dermatitis, an interaction between the TLR2 rs4696480 locus and the FCER1A rs2252226 locus has been linked to disease severity." (PMID 40672946, 2025). "Inflammatory dendritic epidermal cells (IDECs) in skin lesions of atopic dermatitis (AD) express high-affinity IgE receptor (FcεRI) and toll-like receptor 2 (TLR2), which mediate the generation and maintenance of inflammation." (PMID 39086490, 2024). "TLR2 expression and some skin or inflammatory diseases, such as atopic dermatitis and erythema nodosum reprosum, were shown." (PMID 35715478, 2022). "eSkIN also shows that TLRs (TLR1 and TLR2), which are known to promote atopic dermatitis, are downregulated by BM." (PMID 29415693, 2018). "The purpose of the study is to determine the relationship of polymorphisms of genes of Toll-like receptors TLR2 and TLR4 with clinical and immunological parameters in atopic dermatitis patients in a “case-control” study." (PMID 28593178, 2017). "TLR2-mediated inflammation, which helps to fight infections, may exacerbate inflammatory disorders like atopic dermatitis." (PMID 32999082, 2020). "Extensive use of skin detergents is known to augment skin inflammation in atopic dermatitis, which may in part be due to the mobilization of proinflammatory TLR2 agonists." (PMID 30459192, 2018). "The goal of the present research (actually, a random case-control study) was to elucidate how the polymorphisms of genes TLR2 and TLR4, which encode the TLR2 and TLR4 receptors of the immune response system, are associated with clinical and immunological indicators of atopic dermatitis." (PMID 28593178, 2017). "No homozygous carriers of the TLR2 R753Q single nucleotide polymorphism were found in the atopic dermatitis and control groups." (PMID 28443596, 2017). "A recent study showed that canonical TLR2 signaling may offer a novel therapeutic approach to barrier recovery in atopic dermatitis and ulcerative colitis." (PMID 25915861, 2015).
atopic dermatitis (continued). "Genetic variation in TLR2, TLR4, TLR10 and TLR1TLR6 and TLR10 have been associated with the development of asthma, and in TLR9 a promoter polymorphism has been associated with atopic eczema." (PMID 22857391, 2012). "Therefore, TLR2 plays an important role in the pathogenesis of atopic dermatitis and may be involved in enhanced S. aureus skin infection." (PMID 40006996, 2025). "Furthermore, TEO likely alleviates inflammation by suppressing the TLR2/STAT3 signaling pathway, as evidenced by the anti-inflammatory effects of Cupressaceae terpenoids in atopic dermatitis models." (PMID 41471858, 2025). "Oleamide could be used for the treatment of inflammatory diseases connected with abnormal expression or activation of Toll-like receptor 2 (TLR2) and 4 (TLR4) and their adapter proteins, especially for peripheral inflammatory disorders, such as atopic dermatitis." (PMID 32369935, 2020).
influenza (34 papers, 2012 to 2026). An acute viral infection of the respiratory tract, occurring in isolated cases, in epidemics, or in pandemics; it is caused by serologically different strains of viruses (influenzaviruses) designated A, B, and C, has a 3-day incubation period, and usually lasts for 3 to 10 days. "A reduction in influenza-associated secondary pneumococcal infections has been reported in mice co-administered with inhaled TLR2 agonists and inactivated vaccines, highlighting the effectiveness of TLR agonists in influenza vaccines." (PMID 41568029, 2025). "A reduced influenza-associated secondary pneumococcal infections has been reported in mice with co-administration of an inhaled TLR2 agonist with an inactivated vaccine, also highlight the effectiveness of TLR agonist use in influenza vaccine." (PMID 38179453, 2023). "TLR2 has been implicated in promoting clearance of the pneumococcus, and stimulation of this receptor has been shown to protect against influenza infection." (PMID 25166617, 2014). "An example of such an application is modelling the effect of treatments that modulate the innate immune response, such as the toll-like receptor-2 agonist Pam2Cys which has been shown to stimulate innate immune signals and reduce influenza-associated mortality and morbidity in animal studies." (PMID 30653522, 2019). "Based on the observation that TLR2 deficiency led to increased transmission, we hypothesized that the innate immune response to co-infection with the pneumococcus and influenza differed between these two groups." (PMID 25166617, 2014). "A549 cells infected with influenza and treated with curcumin showed inhibition of influenza-induced expression of TLR2, TLR4, and TLR7, as well as inhibition of activation of MyD88- and TRIF-dependent signaling pathways." (PMID 34282358, 2021). "Together, these data suggest that BCG-CWS can be promising as a potential influenza vaccine adjuvant in both young and old aged population through TLR2/4-mediated immune-boosting activities." (PMID 34063125, 2021). "Stimulation of TLR2 has shown promise for improving health in influenza-bacteria dual-infected animals." (PMID 30682165, 2019). "Manipulation of TLRs, in particular TLR2, has been shown to improve survival, and microbial clearance in mice co-infected with influenza and bacterial pathogens." (PMID 30682165, 2019). "Similarly, the delivery of an influenza vaccine candidate adjuvanted with a combined TLR2/TLR7 adjuvant elicited higher immune responses than unadjuvanted formulations." (PMID 40176816, 2025). "A previous study from our group showed that an OMV-based vaccine containing the M2e antigen generated using the CC strain and administered via the subcutaneous route stimulated a protective immune response in mice against influenza and retained TLR2 agonist activity." (PMID 39066362, 2024). "Therefore, the aim of this study was to evaluate an experimental mucosal influenza vaccine based on recombinant NP formulated with a diacylated lipopeptide ligand of the TLR2/6 heterodimer, the BPPcysMPEG." (PMID 36986773, 2023). "Activation of the TLR family member TLR2 and its related signaling pathways has been shown to induce the innate immune response, which can then resist various respiratory virus infections, including influenza and the globally dominant SARS-CoV-2 viruses." (PMID 37896995, 2023). "We speculate that influenza-induced IFN-β reprograms the macrophage transcriptional response to TLR2 agonists, such that expression of neutrophil chemokine genes is repressed, leading to the observed increased sensitivity to 2° bacterial infection." (PMID 31064834, 2019). "Via TLR-2 and TLR-4, such vaccine formulation promoted the induction of robust Ab and Th1-/Th17-type cellular responses and when associated with inactivated Influenza vaccine, generated a protective immunity against Influenza challenge." (PMID 29563912, 2018).